CXCR2 (C-X-C motif chemokine receptor 2)
Diseases named in the same sentence as CXCR2 in open-access papers (continued):
Sharing a sentence is not in itself a finding about the gene and the disease.
ovarian carcinoma (continued). "CXCR3/4/7 are potential therapeutic targets, and CXCR2/4/5/6/7 are new markers for the prognosis of ovarian cancer." (PMID 33829065, 2021). "Based on three algorithms (TIMER, quanTIseq, and xCell), we noticed the prominent interaction between CXCR2 and macrophage in ovarian cancer tissues." (PMID 34840630, 2021). "This notion is also supported by a previous study showing that inhibition of CXCR2 by use of SB225002 also decreases peritoneal metastasis of ovarian cancer cells in a similar experimental model." (PMID 34115261, 2021). "To identify CXCR2-relevant genes, we separated ovarian cancer patients into high- and low-expression groups in line with the median value of CXCR2 expression." (PMID 34840630, 2021). "For the present study, we correlated the expression of IL‐8 and its receptors (CXCR1, CXCR2) with clinical measures (staging, tumour grade and overall survival) in patients with ovarian cancer." (PMID 31793192, 2020). "By studying the expression levels of IL‐8, CXCR1 and CXCR2 in different human ovarian cancer cell lines (SKOV3, A2780), we confirmed the expression of IL‐8 and its receptors in all cell lines tested." (PMID 31793192, 2020). "To identify the expression of IL‐8, CXCR1 and CXCR2 in serous ovarian cancer, we collected patients with ovarian cancer from West China Second University Hospital." (PMID 31793192, 2020). "To confirm the expression of CXCR1 and CXCR2 in ovarian cancer cells, we employed immunocytochemistry and found CXCR2 was mainly expressed in the ovarian cancer cells." (PMID 31793192, 2020). "In summary, CXCR2-driven ovarian cancer progression directly upregulates its own ligands such as CXCL1 and CXCL2." (PMID 29515768, 2018). "High expression of CXCR2 or its ligand CXCL1 leads to increased ovarian cancer proliferation, which is believed to be partly mediated by transactivation of EGFR signaling, and the suppression of CXCR2 leads to apoptosis." (PMID 29515768, 2018). "Our previous study confirmed the role of NF-κB signaling through EGFR-transactivated Akt on the CXCR2-driven ovarian cancer progression." (PMID 29515768, 2018). "Although CXCR2 regulates cell cycle through multiple signaling pathways, the mechanistic effects of CXCR2 on ovarian cancer cell proliferation is poorly understood." (PMID 29515768, 2018). "Patients with highly CXCR2 expressed ovarian cancer had short survival compared to patients with low CXCR2 levels." (PMID 29515768, 2018). "CXCR2-positive ovarian cancer cells significantly increased in proliferation compared to negative cells." (PMID 29515768, 2018). "As expected, CXCR2 was highly expressed on MDSCs, especially G-MDSCs, in ascitic fluid samples from human ovarian cancer." (PMID 29703902, 2018). "CXCR2-positive cells proliferated faster than CXCR2-negative cells, indicating that CXCR2 is a proliferative factor in ovarian cancer." (PMID 29515768, 2018).
ovarian carcinoma (continued). "Another study demonstrated that omentum-secreted IL-8 and GRO-α can activate C-X-C motif chemokine receptor 2 (CXCR2) in ovarian carcinoma cells and facilitate EOC cell spreading in the peritoneal cavity." (PMID 30445726, 2018). "Particularly, the NF-κB mediated signaling, a well-established dominant transduction pathway for the development and progression of a variety of tumors, was involved in CXCR2-driven ovarian cancer progression." (PMID 27723802, 2016). "Molecules such as VEGFA, MMP11 and TGF -β1 in particular CXCR2 play a very important role on cancer progression including ovarian cancer progression and hence their expressions with or without siRNA after anesthetic exposure were further determined." (PMID 27028996, 2016). "The CXCR2 was frequently expressed in tumors obtained from patients with ovarian cancer, prompting ovarian cancer progression." (PMID 27723802, 2016). "In our recent study, potentiating NF-κB activation through EGFR-transactivated Akt augmented proinflammatory chemokines CXCL1/2, contributing to CXCR2-driven ovarian cancer progression." (PMID 27723802, 2016). "Based on parental SKOV-3 ovarian cancer cell line, we generated stable CXCR2 transfected cells (SKCXCR2) as well as control cells transfected with empty vector (SKA)." (PMID 27723802, 2016). "In conclusion, CXCR2-driven ovarian cancer progression in the peritoneal cavity involves NF-κB mediated CCL20 as a main chemokine network, which would lead to new approaches of ovarian cancer progression and treatment." (PMID 27723802, 2016). "The present study confirms CXCR-2 as a novel therapeutic target to control anaesthetic mediated effects on ovarian cancer cell biology." (PMID 27028996, 2016). "We previously demonstrated that CXCR2-driven ovarian cancer progression potentiated NF-κB activation through EGFR-transactivated Akt." (PMID 27723802, 2016). "In this context, blockade or silencing of CXCR2 gene attenuated human pancreatic tumor growth and arrested ovarian carcinoma cells at G0/G1 and G2/M." (PMID 24593195, 2014). "In summary, CXCR2 expressing ovarian cancer cells potentiated NF-κB activation via EGFR-transactivated Akt signaling to induce CXCL1/2 secretion as an autocrine or paracrine growth factor." (PMID 24376747, 2013). "Among chemokine receptors, ovarian cancer cells frequently express CXCR2, which has prompted ovarian cancer progression." (PMID 24376747, 2013). "Particularly, tumor necrosis factor (TNF), abundantly expressed in ovarian cancer, enhanced cell proliferation by decreasing the G0-G1 phase in CXCR2 transfected cells." (PMID 24376747, 2013). "We then defined the impact of NF-κB signaling, a main proinflammatory pathway, on the potential contribution of CXCR2 to ovarian cancer progression." (PMID 24376747, 2013). "Here we used parental ovarian cancer cell lines and generated stable CXCR2 transfected cells as well as control cells transfected with empty vector." (PMID 24376747, 2013). "We demonstrated here that CXCR2 transiently-transfected human (SKOV-3) ovarian cancer cells similarly increased CXCL1 promoter activities via a critical proximal κB site." (PMID 24376747, 2013). "In addition, we found that OC-MQs increased CXCR1 and CXCR2 expression, including in ovarian cancer cells." (PMID 39937005, 2025). "CXCR2 is crucial for the acquisition of cisplatin chemoresistance of ovarian cancer cells." (PMID 34840630, 2021). "In addition, inhibition of CXCR2 reduces tumorigenesis and angiogenesis in the lung, oesophageal and ovarian cancer." (PMID 34124076, 2021). "CXCR2 overexpression has been demonstrated to promote ovarian cancer progression." (PMID 34474677, 2021).
ovarian carcinoma (continued). "This indicated that CXCR2 amplification contributed to its overexpression in ovarian cancer." (PMID 34840630, 2021). "The mRNA of CXCR 2/4/5/6/7 can be used as indicators for predicting ovarian cancer progression." (PMID 33829065, 2021). "Moreover, high expression of CXCR2 contributes to carcinogenesis in diverse cancer types, especially ovarian cancer." (PMID 34840630, 2021). "In contrast, we noticed the positive associations of CXCR2 with the abundance of CD8+ naïve T cell, CD4+ central memory T cell, CD4+ Th2 T cell, CD4+ Th1 T cell, common lymphoid progenitor, and B cell plasma across ovarian cancer." (PMID 34840630, 2021). "Herein, this study observed the functions of CXCR2 in prognosis and immunology of ovarian cancer." (PMID 34840630, 2021). "We noticed that amplification of CXCR2 occupied the relatively high alteration frequency in ovarian cancer, which could contribute to the upregulation of CXCR2 expression." (PMID 34840630, 2021). "Moreover, it participated in modulating immune cell infiltration in the tumor microenvironment of ovarian cancer such as macrophage and immune response was prominently modulated by CXCR2." (PMID 34840630, 2021). "Moreover, prognostic significance of CXCR2 expression should be verified in a larger ovarian cancer cohort." (PMID 34840630, 2021). "A large number of studies have shown that the ligand IL-8 of CXCR1/CXCR2 is abnormally increased in the plasma of patients with ovarian malignant tumors and is positively correlated with the clinical stage and pathological type of epithelial ovarian tumor (EOC)." (PMID 33829065, 2021). "Furthermore, CXCR2 was significantly related with poor overall survival of patients with ovarian cancer." (PMID 31793192, 2020). "Thereby, the IL‐8 and its receptors, especially CXCR2, may be important mediators of ovarian cancer metastasis." (PMID 31793192, 2020). "To further determine whether the IL‐8 and its receptors were associated with prognosis of patients with ovarian cancer, we subjected the IL‐8, CXCR1 and CXCR2 to survival analysis using the online database (Gene Expression Profiling Interactive Analysis)." (PMID 31793192, 2020). "Furthermore, CXCR-1 and CXCR-2 were also demonstrated to be strongly expressed in ovarian cancer cell lines, and to activate mitogen-activated protein (MAP) kinase via EGFR, contributing to cell migration and proliferation." (PMID 31703453, 2019). "Since G-MDSCs mainly express CXCR2 in human samples, a CXCR2 antagonist could be an effective treatment for ovarian cancer patients." (PMID 29703902, 2018). "In spite of no change in EGFR activation after cancer spreading of SKA and SKCXCR2 cells, the NF-κB signaling pathway appears to conserve CXCR2-driven ovarian cancer progression throughout the whole process including initiation, promotion and progression phases." (PMID 27723802, 2016). "These facts support a critical role of CXCR2 in ovarian cancer progression." (PMID 27723802, 2016). "Moreover, as described in detail previously, the molecular mechanism involved in the cancer progression indicates the significant role of NF-κB signaling, a main proinflammatory pathway, on the potential contribution of CXCR2 in ovarian cancer progression." (PMID 27723802, 2016). "CXCR2 has been shown to be overexpressed in ovarian cancer cell lines and to promote cancer metastasis and so its role in anaesthetic-mediated effects on tumour biology was investigated: after transfection with CXCR2 siRNA, the post-exposure expression of CXCR, was all reduced significantly." (PMID 27028996, 2016).
ovarian carcinoma (continued). "Here, we identified the chemokine signature involved in CXCR2-driven ovarian cancer progression using a mouse peritoneal xenograft model for ovarian cancer spreading with CXCR2-negative (SKA) and positive (SKCXCR2) cells generated previously from parental SKOV-3 cells." (PMID 27723802, 2016). "Therefore, to clarify CXCR2 axis in the progression of CXCR2-driven ovarian cancer, we performed the comprehensive chemokine network analysis in the ovarian tumor tissues using PCR array." (PMID 27723802, 2016). "Our recent studies in endometrial and ovarian cancer suggested that CXCL1 and/or CXCL8 secreted by human cancer cells and signalling via their receptors CXCR1 and/or CXCR2 could be implicated in human ASC migration." (PMID 27241286, 2016). "Here, we employed the mouse peritoneal spreading model for ovarian cancer and identified a main signaling pathway and chemokine network involved in CXCR2-driven ovarian cancer progression using tumor tissues of the omentum, a main metastasis site for ovarian cancer." (PMID 27723802, 2016). "Of interest CXCR2 expressing ovarian cancers are aggressive with poor outcomes." (PMID 25372289, 2014). "Thus augmentation of proinflammatory chemokines CXCL1/2, by potentiating NF-κB activation through EGFR-transactivated Akt, contributes to CXCR2-driven ovarian cancer progression." (PMID 24376747, 2013). "CXCR2 expressing ovarian cancers are aggressive with poorer outcomes." (PMID 24376747, 2013). "Also, CXCR2-expressing ovarian cancer is aggressive with undesirable clinical outcomes." (PMID 34840630, 2021). "Therefore, we first asked whether NF-κB plays critical role in CXCR2-mediated CCL20 regulation to elucidate the signaling pathway involved in the induction of CCL20 during ovarian cancer progression." (PMID 27723802, 2016). "Therefore inhibition of the CXCL1/2-CXCR2 axis may be an effective preventive or therapeutic action against CXCR2-driven ovarian cancer progression." (PMID 24376747, 2013). "For this reason, the use of CXCR2 inhibitors in combination with a drug targeting VEGF yields better results, as shown by experiments on glioblastoma multiforme and ovarian cancer." (PMID 40427171, 2025). "The expression of CX3CR1 was also significantly related to chemokine receptors, including CXCR2 (R = 0.54, P < 2.2e−16) and CCR5 (R = 0.43, P < 2.2e−16) in epithelial ovarian cancer." (PMID 38241595, 2024). "The most extensively studied CXCR2 inhibitor is SB225002: (N-(2-hydroxy-4-nitrophenyl)-N′-(2-bromophenyl)urea), which exhibits antitumor activity against cervical cancer, ovarian cancer, and androgen-independent prostate cancer." (PMID 37108425, 2023). "Activated CXCR2 can also indirectly activate ERK MAPK via the transactivation of epidermal growth factor receptor (EGFR), in a mechanism identified in ovarian cancer cells." (PMID 35216283, 2022). "Blocking CXCR2 with SB225002 has proved to inhibit tumor progression in breast cancer, ovarian cancer, acute myeloid leukemia, and nasopharyngeal carcinoma." (PMID 35011369, 2021). "Hence, CXCR2 might act as a promising prognostic predictor of ovarian cancer." (PMID 34840630, 2021). "An CXCR2 antagonist suppresses MDSC infiltration and inhibits ovarian cancer progression through the Snail/NF-kB axis." (PMID 35011369, 2021). "To investigate the possible role of IL‐8 in ovarian cancer, we exogenously activated or inhibited IL‐8 effect in ovarian cancer cells using IL‐8 or Reparixin (inhibitor of both IL‐8 receptors CXCR1, CXCR2)." (PMID 31793192, 2020).
ovarian carcinoma (continued). "Alternatively, patients with more advanced ovarian cancer (those with lower differentiation, distant metastasis and advanced FIGO stage) had increased tumoral IL‐8, CXCR1 and CXCR2 expression." (PMID 31793192, 2020). "As in mouse MDSCs, MDSCs from human ovarian cancer ascitic fluid samples were attracted by CXCL1, CXCL2, and CXCL5, and a CXCR2 antagonist inhibited this migration." (PMID 29703902, 2018). "Particularly, ovarian cancer cell lines express high levels of proinflammatory chemokines CXCL1-3 and CXCL8 as specific ligands for the chemokine receptor CXCR2." (PMID 27723802, 2016). "All these evidence strongly support our conclusion that up-regulation of both CXCR2 and TGF-β promote the change of ovarian cancer towards a more invasive phenotype." (PMID 27028996, 2016). "Taken together, the progression of ovarian cancer in the peritoneal cavity involves NF-κB-mediated CCL20 as a main chemokine network, which is potentiated by CXCR2 expression." (PMID 27723802, 2016). "Overexpression of CXCR2 increased EGFR-transactivated Akt and Erk in ovarian cancer cells such as SKOV-3 and OVCAR-3." (PMID 27723802, 2016). "These facts support the expectation that NF-κB is mainly involved in the progression of CXCR2-driven ovarian cancer, leading to augmentation of CXCR2 ligands such as CXCL1-3 and 5–8 followed by proinflammatory tumor microenvironment via CXCR2 axis." (PMID 27723802, 2016). "CXCL1 selectively binds to CXCR2, a G-protein-coupled receptor (GPCR) that has been shown to transactivate EGFR in ovarian cancer and non-small cell lung cancer." (PMID 26462152, 2015). "In our previous study, ovarian cancer cell lines highly expressed CXCL1-3 and CXCL8 which all have a high affinity for CXCR2." (PMID 24376747, 2013). "Snail knockdown inhibited the growth of HM-1 mouse ovarian cancer cell in immunocompetent mice, accompanied by an increase in CD8+ TILs and a decrease in MDSCs, by reducing the levels of the (C-X-C Motif) chemokine receptor 2 (CXCR2) ligands, chemokine (C-X-C motif) ligand 1/2 (CXCL1/2)." (PMID 36823234, 2023). "By activating CXCR2, CXCL1 increases the proliferation of ovarian cancer cells." (PMID 37108425, 2023). "In ovarian cancer, Snail promotes the MDSC process via CXCR2." (PMID 36290882, 2022). "This may help to create targeted therapy for ovarian cancer, in which angiogenesis is inhibited by a blockage of NF-κB, suppressing VEGF and IL-8 activity, or by targeting CXCR2, the key receptor for the GRO-alpha and IL-8 chemokine activity." (PMID 33266317, 2020). "CXCR2 is activated by cancer-promoting IL-8 and CXCL1 and could transactivate EGFR in ovarian cancer and non-small cell lung cancer." (PMID 26462152, 2015). "We generated CXCR2 positive (SKCXCR2) and negative (SKA) cell lines by stably transfecting CXCR2 or empty vectors into parental SKOV-3 ovarian cancer cells." (PMID 24376747, 2013). "To exclude an SKOV-3 cell-type specific response, we confirmed our data by generating another CXCR2 positive (OVCXCR2) versus a negative (OVA) cell line using parental OVCAR-3 ovarian cancer cells which either entirely lack or have trace amounts of CXCR2." (PMID 24376747, 2013). "Because inflammation-driven ovarian cancer was found to enhance CXCL1-3 expression, - targeting CXCR2, a specific receptor for CXCL1-3, may be a therapeutic strategy as suggested by others." (PMID 23800251, 2013). "We therefore investigated molecular mechanisms involved in CXCR2-driven cancer progression by comparing CXCR2 positive and negative ovarian cancer cell lines." (PMID 24376747, 2013).